PRELID1 (PRELI domain containing 1)
Description:
Involved in the modulation of the mitochondrial apoptotic pathway by ensuring the accumulation of cardiolipin (CL) in mitochondrial membranes. In vitro, the TRIAP1:PRELID1 complex mediates the transfer of phosphatidic acid (PA) between liposomes and probably functions as a PA transporter across the mitochondrion intermembrane space to provide PA for CL synthesis in the inner membrane. Regulates the mitochondrial apoptotic pathway in primary Th cells. Regulates Th cell differentiation by down-regulating STAT6 thereby reducing IL-4-induced Th2 cell number. May be important for the development of vital and immunocompetent organs.
Synonyms: PRELI; CGI-106; SBBI12; PX19
Tractability: Small molecule: a structure with a bound ligand is known. PROTAC: ubiquitination databases record sites on it; its protein half-life has been measured.
Gene: Protein-coding gene on chromosome 5 (177,303,790 to 177,306,949, forward strand). Ensembl gene ENSG00000169230.
Subcellular location: Mitochondrion; Mitochondrion intermembrane space
Subcellular location (Human Protein Atlas): Mitochondria; Nucleoplasm
Pathways (Reactome):
Metabolism of proteins: Mitochondrial protein degradation
Gene Ontology:
Molecular function: phosphatidic acid transfer activity; protein binding
Biological process: negative regulation of apoptotic process; negative regulation of mitochondrial membrane potential; negative regulation of release of cytochrome c from mitochondria; positive regulation of cellular respiration; positive regulation of endopeptidase activity; positive regulation of phospholipid transport; positive regulation of T cell apoptotic process; regulation of membrane lipid distribution; regulation of mitochondrial membrane potential; regulation of T cell differentiation; phospholipid transport
Cellular component: mitochondrial intermembrane space; mitochondrion; protein-containing complex
Genetic constraint (gnomAD): Loss-of-function variants: 15 observed, 30.79 expected, observed/expected ratio (o/e) 0.49, 90% interval 0.32 to 0.75. The synonymous counts are far from expectation, so gnomAD's model fits this gene poorly and the ratio says little. Missense variants: 187 observed, 277.99 expected, observed/expected ratio (o/e) 0.67, 90% interval 0.6 to 0.76. Synonymous variants: 79 observed, 107.29 expected, observed/expected ratio (o/e) 0.74, 90% interval 0.61 to 0.89.
Homologues: Orthologues: chimpanzee PRELID1 (99% identical), macaque PRELID1 (99% identical), dog PRELID1 (99% identical), guinea pig PRELID1 (98% identical), rabbit PRELID1 (97% identical), rat Prelid1 (97% identical), mouse Prelid1 (96% identical), pig PRELID1 (93% identical), tropical clawed frog prelid1 (78% identical), zebrafish prelid1a (69% identical), zebrafish prelid1b (49% identical), Drosophila melanogaster prel (38% identical), and 1 more. Paralogues in human: PRELID3B (26% identical), PRELID3A (21% identical), PRELID2 (16% identical).
Diseases named in the same sentence as PRELID1 in open-access papers:
PRELID1 is named in the same sentence as 11 diseases in open-access papers, as found by Europe PMC text mining. Sharing a sentence is not in itself a finding about the gene and the disease. The quoted sentences say what the papers report.
breast carcinoma (2 papers, 2020). "Prelid1 is a prognostic gene in breast cancer that forms a complex in the mitochondrial intermembrane space to prevent apoptosis, and BACE2 (beta-secretase 2) plays a role in melanosome amyloid formation during melanocyte differentiation." (PMID 32831131, 2020).
liver cancer (2 papers, 2023 to 2024). An epithelial or non-epithelial malignant neoplasm that arises from the liver. "Moreover, our results showed that PRELID2 promotes the proliferation and metastasis of liver cancer cells by enhancing ROS generation, which is similar to the function of PRELID1 in increasing ROS production." (PMID 38124228, 2023).
endometrial cancer (1 paper, 2022). Primary or metastatic malignant neoplasm involving the endometrium (mucous membrane that lines the endometrial cavity). "SNRPC, PRELID1, EIF2S2, and NDUFB9, four of the model’s genes, were discovered to have higher levels of expression in endometrial cancer than in nearby tissues (*P<0.05, **P<0.01, ***P<0.001)." (PMID 36185238, 2022). "We created an LLPS-related predictive model for endometrial cancer by extensive study, and it consists of four genes: EIF2S2, SNRPC, PRELID1, and NDUFB9." (PMID 36185238, 2022). "EIF2S2, SNRPC, PRELID1, and NDUFB9 were all up-regulated in endometrial cancer tissues, according to PCR results." (PMID 36185238, 2022).
glioma (1 paper, 2021). A benign or malignant brain and spinal cord tumor that arises from glial cells (astrocytes, oligodendrocytes, ependymal cells). "This study aimed to show that pseudogene PRELI domain-containing 1 pseudogene 6 (PRELID1P6) promotes glioma progression." (PMID 34108621, 2021).
mesothelioma (1 paper, 2021). A usually malignant and aggressive neoplasm of the mesothelium which is often associated with exposure to asbestos. "Clonal positive selection (dN/dS>1) involved five tumour suppressors NF2, BAP1, SETD2 which were independently validated in the mesothelioma TCGA7, FBXW7 and PRELID1." (PMID 33741915, 2021).
uveal melanoma (1 paper, 2023). A melanoma derived from melanocytes of the uveal tract. "To verify our computational findings, we tested the mRNA expression level of CCL18, CXCL8, GTPBP1, JAG2, PRELID1 and PTGER4 in uveal melanoma cell lines: M17, M23 and SP6.5 and normal uveal epithelial cell: Um95." (PMID 36597071, 2023).
cancer (4 papers, 2019 to 2022). A tumor composed of atypical neoplastic, often pleomorphic cells that invade other tissues. "Gillen and colleagues discovered that PRELID1’s alternative polyadenylation controls mitochondrial ROS signaling and the development of cancer." (PMID 36185238, 2022). "Increased levels of PRELID1 expression led to enhanced tumor cell growth and substantially lowered the survival of cancer patients." (PMID 35487956, 2022). "According to certain studies, the four model genes EIF2S2, SNRPC, PRELID1, and NDUFB9 have significant roles in the development of cancer." (PMID 36185238, 2022).
PRELID1 also shares sentences with these, for which no sentence is quoted: tumor (2 papers); asthma (1); cholelithiasis (1); colorectal cancer (1).